ERBB2 (erb-b2 receptor tyrosine kinase 2)
Diseases named in the same sentence as ERBB2 in open-access papers (continued):
Sharing a sentence is not in itself a finding about the gene and the disease.
breast cancer (continued). "Patients who have tumors that are positive for ERBB2, accounting for 15% to 20% of breast cancer cases, are treated with a combination of ERBB2-targeted therapy and chemotherapy." (PMID 36540440, 2022). "Despite the initial benefit from treating ERBB2-positive breast cancer with tyrosine kinase inhibitor lapatinib, resistance develops inevitably." (PMID 35431974, 2022). "Statin combination therapies have been studied in relation to HER2-positive (also known as Erbb2-positive) breast cancer." (PMID 36579200, 2022). "rH/E distinguishes the HER2-enriched subtype breast cancer better than ERBB2 or ESR1 expression alone, which can help to more accurately identify the subgroups of tumor which are predominantly driven by HER2 or ER in the HR+/HER2+ population." (PMID 36620573, 2022). "It explicitly inhibits EGFR and ERBB2 tyrosine kinase receptors in tumor cells, showing better therapeutic efficacy and limited toxicity in gallbladder and breast cancers than GW-572016." (PMID 36476719, 2022). "The tyrosine kinase receptor ErbB2 (also referred to as HER2) is well-known for its oncogenic activity in breast cancer (BCa), but it also plays an important role in both cardiac embryonic development and in the adult heart." (PMID 36097051, 2022). "In the analysis of 5,605 cases of breast cancer, ERBB2 was altered in 12.5% of all genes, with 10.6% of amplifications, 2.4% of mutation, and 0.7% of the combination of amplification and mutation." (PMID 36172165, 2022). "In this nonrandomized clinical trial, treatment with the neoadjuvant atezolizumab, docetaxel, trastuzumab, and pertuzumab regimen in patients with stage II or III ERBB2-positive breast cancer appears to have had an acceptable pCR rate and modest toxic effects." (PMID 35797012, 2022). "The ERBB2, which ranked 16th in DriverRWH, is confirmed to be related to breast cancer, but it ranked 35th in OncodriveFML, 126th in MutsigCV, and even 1465th in Gravity." (PMID 35831792, 2022). "Clinical evidence supporting a role of immunotherapy combinations in ERBB2-positive breast cancer are limited." (PMID 35797012, 2022). "Breast cancer is a heterogeneous disease stratified by hormone receptor and human epidermal growth factor (ErbB2/(Her2/neu)) receptor status." (PMID 36531159, 2022). "Overexpression of HER-2/ErbB2 occurs in 20% of all breast cancer subtypes, and it can control processes such as cellular growth, apoptosis, proliferation, differentiation, angiogenesis, and invasion by regulating PI3K/AKT and MAPK/ERK signalling pathways." (PMID 36077593, 2022). "Recent large-scale cancer genomic datasets show the overlap between CCND1 amplification and ERBB2 amplification in breast cancer patients." (PMID 35742993, 2022). "Epidermal growth factor receptor (EGFR/ErbB1), is onemember of this family, over expressed in 20% to 80% of breast cancers, and another member is HER2 (ErbB2/neu), is amplified and/or over expressed (i.e., HER2-positive) in 20%to 30% of breast cancers." (PMID 37654845, 2022). "Trastuzumab, a humanized monoclonal antibody developed initially for breast cancer, specifically recognizes the HER2 protein encoded by the ERBB2 gene." (PMID 36291900, 2022). "Despite its success as an ErbB2-positive breast cancer treatment, lapatinib has raised concern on gastrointestinal toxicity, specifically diarrhoea, which affects 78% of patients." (PMID 35800225, 2022). "Albeit rare, an ERBB2 fusion identified in a patient with HER2+ breast cancer and an acquired RET fusion identified in a patient with an acquired ESR1, offer interesting insights into subtype-specific resistance mechanisms and warrant further investigation." (PMID 36470901, 2022).
breast cancer (continued). "We then established two lapatinib-resistant ERBB2-positive breast cancer cell lines (SKBR3-lapR and BT474-lapR) in our lab following the published protocol." (PMID 35431974, 2022). "Alternatively, genomic tests have been reported recently in determining the ER (ESR1), PR (PGR), and HER2 (ERBB2) status in breast cancer." (PMID 35006257, 2022). "Numerous genes located in 17q12 region have been implicated in diverse cancers, such as ERBB2 for gastric cancer 38 and breast cancer 39, CDK12 for prostate cancer 40, and STARD3 for breast cancer." (PMID 36147475, 2022). "Unfortunately, the higher population of patients with ERBB2-positive late-stage breast cancer will further incur higher cancer-related drug costs." (PMID 36159262, 2022). "Trastuzumab is a valuable therapy option for women with ERBB2(HER2)+ breast cancer tumours, often used in combination with chemotherapy and alongside other therapies." (PMID 36454979, 2022). "In particular, homologs AKT1, AKT2, ERBB2, FGFR2, and PIK3CA in CGC play important roles in breast cancer progression, mediating breast cancer risk, corresponding to the driver candidates RPS6KA1, SGK1, PTK2, IGF1R, PIK3CB, and PRKDC predicted by DriverMP." (PMID 38091511, 2022). "Based on the SOPHIA trial, a three-state Markov model was developed to compare the cost and efficacy of margetuximab to trastuzumab for previously treated women with ERBB2-positive advanced breast cancer." (PMID 36159262, 2022). "Another possible application of our finings is to use BLNK as a predictive marker in ErbB2-positive breast cancer." (PMID 35933456, 2022). "Labeling with ErbB2 or HER2 antibodies can improve the sensitivity and specificity of breast cancer detection." (PMID 35745854, 2022). "Originally it was used only for treating Her-2 positive breast cancers, but later the range of applications was expanded to include ErbB2/Her2-positive gastro-oesophageal cancers." (PMID 36498915, 2022). "Overall, NRG1 appears to induce undesired effects on HER2+ breast cancer cells, ranging from increased proliferation and motility, and resistance to anti-ERBB2 agents." (PMID 35664762, 2022). "ERBB2 is often overexpressed in breast cancer due to gene amplification, and at least three spliced isoforms with clinical relevance have been identified." (PMID 35044822, 2022). "Lapatinib, an orally administered small-molecule tyrosine kinase inhibitor (SM-TKI), is an effective treatment for ErbB2-positive breast cancer." (PMID 35800225, 2022). "Clinical doses of ionizing radiation are known to stimulate the invasive properties of ErbB2-positive breast cancer cells and, moreover, radiation resulted in activation of ErbB2, which, through activation of FoxM1, promoted invasion of breast cancer cells." (PMID 35625825, 2022). "We found previously that ErbB2 downregulates IRF6 in breast cancer cells by activating protein kinase MEK." (PMID 35933456, 2022). "The short form isoform of RON (sf-RON) and ERBB2 are overexpressed in human breast cancer and correlate with poor prognosis." (PMID 36288160, 2022). "For example, HER2/neu (receptor tyrosine-protein kinase erbB-2) gene amplification is observed in approximately 15% of breast cancers." (PMID 35203305, 2022). "Hormonal therapy, targeting ER, and small-molecule and antibody therapies, targeting ErbB2, have significantly improved treatments for ER+ and HER2+ breast cancer patients." (PMID 36011019, 2022). "ERBB2, a member of the ERBB family of receptor tyrosine kinases (RTKs) (EGFR/ERBB1, ERBB2, ERBB3, and ERBB4), is overexpressed in approximately 15–20% of human breast cancers and its expression is highly associated with poorer overall survival." (PMID 35431974, 2022). "ERBB2 is a member of the epidermal growth factor (EGF) receptor family that is over-expressed in up to 20–30% of human breast cancer." (PMID 35897965, 2022).
breast cancer (continued). "The role of ERBB2 as an important predictor of patient outcome and response to various therapies in breast cancer has been clearly established." (PMID 35186034, 2022). "Overall, our data suggest that NRG1 induces the proliferation of SKBR3 (HER2+) breast cancer cells, and partially or completely impairs the efficacy of anti-ERBB2 agents." (PMID 35664762, 2022). "The median (IQR) time from MBC diagnosis to brain radiotherapy ranged from 7.5 (2.3-17.4) months for patients with TNBC to 19.8 (12.2-35.1) months for those with ERBB2-positive/HR-positive breast cancer." (PMID 35960523, 2022). "Tumors that lack estrogen receptor, progesterone receptor, or ERBB2 molecular markers, referred to as triple-negative, make up 15% of breast cancer cases and are generally treated with chemotherapy." (PMID 36540440, 2022). "The European Society for Medical Oncology consensus also highlights therapy-related CV toxicity in breast cancer patients receiving specific chemotherapy, anti-ErbB2 target therapy, and left-sided chest RT." (PMID 35621491, 2022). "Correlation also exists between the CB2 receptors expression and estrogen and progesterone receptor, as well as ERBB2/HER-2 levels in breast cancer." (PMID 36291926, 2022). "This platform was developed by them as a prospective novel targeted immunotherapy for HER-2-expressing breast cancer (ERBB2-positive)." (PMID 35209095, 2022). "Anthracycline-based chemotherapy, anti-ErbB2 target therapy, and breast RT are commonly used for patients with breast cancer to prolong survival." (PMID 35621491, 2022). "Novel antibody-drug conjugates targeting ERBB2-low subtypes of advanced breast cancer, such as trastuzumab deruxtecan, have led to longer progression-free survival and overall survival compared to chemotherapy." (PMID 36540440, 2022). "Immunohistochemical characterization of human breast cancer markers (ER, PR, ErbB2/Her2) in mammary tumors from 14 heterozygous mutant female mice revealed heterogeneity in their expression." (PMID 36396684, 2022). "In this study, we explored the correlation between PTPRO and lapatinib resistance in ERBB2-positive breast cancer." (PMID 35431974, 2022). "Since then, large randomised controlled trials and meta-analyses have shown trastuzumab to delay the recurrence of breast cancer and increase survival for women who have ERBB2 positive tumours." (PMID 36454979, 2022). "Another study also suggested that in ErbB2-positive breast cancer, combinative treatment of USP2 inhibitor and Erb2 inhibitor HSP90 demonstrated synergistic therapeutic efficacy." (PMID 36567903, 2022). "Our findings in OAC are consistent with work in ERBB2-amplified breast cancer cells where metabolic adaptations to lapatinib treatment occur which shift the cells towards mitochondrial energy metabolism." (PMID 36153371, 2022). "What are the outcomes of neoadjuvant atezolizumab with docetaxel, trastuzumab, and pertuzumab (PATH) for the treatment of ERBB2-positive early breast cancer?" (PMID 35797012, 2022). "HER2 (ERBB2) has been actively studied in cancer treatment for decades and was a breakthrough therapy for breast cancer." (PMID 35980387, 2022). "On the other hand, CDK12 was the most common co-amplification gene with ERBB2 in breast cancer (59/80, 73.8%), stomach cancer (37/83, 44.6%), biliary tract cancer (33/57, 57.9%) and colorectal cancer (33/55, 60%)." (PMID 35911441, 2022). "Metastatic HER2-positive breast cancers resistant to anti-HER2 therapies are enriched in somatic alterations that promote MEK/ERK signaling, including biallelic loss of NF1 and activating mutations of ERBB2." (PMID 36358725, 2022). "Compared to trastuzumab plus chemotherapy, margetuximab plus chemotherapy has exhibited proven clinical benefits in patients with pretreated ERBB2-positive advanced breast cancer." (PMID 36159262, 2022).
breast cancer (continued). "14-3-3ζ was found to cooperate with other well-established oncogenes (such as ErbB2) to drive a more aggressive malignant phenotype in breast cancer." (PMID 35876652, 2022). "ERBB2 (HER2/NEU) is frequently highly expressed in breast cancers and participates in cell signaling pathways leading to proliferation, angiogenesis and metastasis." (PMID 35625825, 2022). "Metastatic samples showed SLK overexpression in our study, something that has been previously observed in other cancer types such as ErbB2-driven breast cancer." (PMID 35560144, 2022). "We suggest that the NRG1/ERBB3/ERBB2 pathway promotes the anchorage-independent growth of basal-like breast cancer cells." (PMID 35406375, 2022). "A preclinical study shows that lapatinib inhibits the growth of trastuzumab-resistant ERBB2-positive breast cancer cells and increases apoptosis of anti-ERBB2 antibodies." (PMID 35431974, 2022). "In summary, ErbB2-induced BLNK downregulation in detached breast cancer cells is driven by IRF6 downregulation." (PMID 35933456, 2022). "The cancer panel contains 54 genes, including numerous known key driver genes (BRCA1, BRCA2 and ERBB2) in breast cancer." (PMID 35936696, 2022). "ERBB2ΔEx16 was first reported in HER2-overexpressed breast cancer after prolonged targeted treatment with trastuzumab." (PMID 36686783, 2022). "A second early success in the development of kinase inhibitors was targeting HER2+ (ERBB2) breast cancer." (PMID 34958800, 2022). "AFAP1-AS1 upregulation caused by H3K27ac modification enhances the translation of ERBB2 by binding to a mRNA decay factor AU-rich binding factor 1 (AUF1), which leads to trastuzumab resistance in breast cancer." (PMID 36359776, 2022). "Soon after this discovery, it was determined that ERBB2 amplification and/or overexpression occurs in approximately 20% of all breast cancers and that amplification and overexpression corresponds with poor prognosis." (PMID 36519541, 2022). "Elsewhere, miR-1296-5p inhibited the viability of ERBB2-positive breast cancer cells by targeting the ERB2/mTORC1 pathway and inhibits osteosarcoma development by targeting Notch." (PMID 35962353, 2022). "Further investigation of this immunotherapy combination in ERBB2-positive early breast cancer is warranted." (PMID 35797012, 2022). "It is well known that amplification of the 17q12-q21 region is the most common mechanism for ERBB2 activation in breast cancer and that it leads to the simultaneous activation of several other genes." (PMID 35186034, 2022). "ERBB2 is one of the most common oncogenic driver genes; its amplification alterations predominantly occur in about 30% of breast cancer and 20% of gastric cancer cases." (PMID 36276102, 2022). "In HER2-positive breast cancer, the ERBB2 amplification leads to an overexpression of the HER2 protein at the cell plasma membrane, this large amount of HER2 increases the activation of downstream proliferating signaling pathways by HER2 homo- or heterodimers." (PMID 35454795, 2022). "We found that ErbB2 promotes survival of breast cancer cell detached from the ECM by a novel mechanism involving downregulation of transcription factor IRF6 and further downregulation of the cell death-promoting protein BLNK." (PMID 35933456, 2022). "Two established lapatinib resistant ERBB2-positive breast cancer cells, SKBR3-lapR and BT474-lapR, were transfected with the plasmid overexpressing PTPRO." (PMID 35431974, 2022).
breast cancer (continued). "The ERBB1 and ERBB2 inhibitor lapatinib was approved in 2007 after it showed improved outcome in breast cancer patients whose tumors expressed the ERBB2 (HER2) receptor." (PMID 35765648, 2022). "We show here that ErbB2-dependent IRF6 downregulation reduces cellular levels of the pro-apoptotic protein BLNK and that BLNK loss blocks anoikis of breast cancer cells and promotes their tumorigenicity in vivo." (PMID 35933456, 2022). "The first study was a blinded case control study using CTCs from 54 known cases of breast cancer where ERBB2 gain (or its absence) was previously established on biopsied tumor tissue samples by FISH." (PMID 35714131, 2022). "Using the ERBB2 S310F and PIK3CA H3140R mutations in breast cancer as examples, this method was validated in a synthetic plasmid template and xenograft mouse blood samples, with a sensitivity of 96.6%." (PMID 36551512, 2022). "ERBB3 and ERBB2 levels are frequently associated, especially in human breast cancers, where ERBB3/ERBB2 heterodimers function as an oncogenic driver for breast tumor cell proliferation." (PMID 35406375, 2022). "Trastuzumab, pertuzumab, and adotrastuzumab emtansine, are used for the treatment of ErbB2-positive breast cancer; adotrastuzumab emtansine is an antibody–drug conjugate that delivers a cytotoxic drug to cells overexpressing ErbB2." (PMID 36009762, 2022). "The results showed that the CNV of ERBB2 Amp was significantly higher than ERBB2 Fusion + Amp in pan-cancer, gastric cancer, colorectal cancer, and breast cancer (P<0.01)." (PMID 36276102, 2022). "In this sense, the clinical management of HER2 breast carcinomas (tumors with overexpression/amplification of the ErbB2/HER2 oncogene) is still a challenge." (PMID 36139701, 2022). "Polyphenols isolated from extra virgin olive oil inhibit the expression of the HER-2/neu protein (ERBB2), which is correlated with aggressive breast carcinoma." (PMID 36557789, 2022). "The NKAB-ErbB2 increased lysis of ErbB2-positive breast carcinoma cells by peripheral blood-derived NK cells endogenously expressing NKG2D." (PMID 36389699, 2022). "The “HER2-low” nomenclature identifies breast carcinomas (BCs) displaying a HER2 score of 1+/2+ in immunohistochemistry and lacking ERBB2 amplification." (PMID 36038884, 2022). "One notable exception is detection of ERBB2 amplification in breast carcinoma as the critical biomarker for trastuzumab therapy." (PMID 36289203, 2022). "We found that increased BLNK mRNA expression is significantly associated with increased disease-free survival of patients with ErbB2/Her2-positive breast carcinoma." (PMID 35933456, 2022). "About 30% of primary breast carcinomas express ErbB2/Her2 receptor, and about 22% of colorectal cancers express ErbB4/Her4 receptors." (PMID 36498915, 2022). "We present our experience with a manual method of staining for estrogen receptor (ER), progesterone receptor (PR), and receptor tyrosine-protein kinase erbB-2 (HER2/neu) in breast carcinoma." (PMID 35702640, 2022). "ERBB2 mRNA levels have been found to be elevated in 44–54% of mammary carcinomas in cats (6/11 cases and 12/44 cases), although numerous studies have shown that the majority of these tumours do not carry ERBB2 gene amplifications." (PMID 36288160, 2022). "HER2, also known as Neu, ErbB-2, CD340 or p185, is an oncoprotein amplified or over-expressed in ~30% of breast cancers (BC) and other tumours, strongly associated with increased disease recurrence and worse prognosis." (PMID 35814459, 2022). "Tumor size, metastasis to lymph nodes, distant organ metastasis or ER, PR and ERBB2 are usually used as indicators for the clinical classification of breast cancer." (PMID 34034721, 2021). "The general subtyping of breast cancer is based on the presence of transmembrane and intracellular receptors, namely, estrogen (ER), progesterone (PR) and the human epidermal growth factor receptor 2 (HER2, also referred to as ERBB2)." (PMID 33179151, 2021).